RNASET2 (ribonuclease T2)
Description:
Ribonuclease that plays an essential role in innate immune response by recognizing and degrading RNAs from microbial pathogens that are subsequently sensed by TLR8. Cleaves preferentially single-stranded RNA molecules between purine and uridine residues, which critically contributes to the supply of catabolic uridine and the generation of purine-2',3'-cyclophosphate-terminated oligoribonucleotides. In turn, RNase T2 degradation products promote the RNA-dependent activation of TLR8. In plasmacytoid dendritic cells, it cooperates with PLD3 or PLD4 5'->3' exonucleases to process RNA fragments and release 2',3'-cyclic guanosine monophosphate (2',3'-cGMP), a potent stimulatory ligand for TLR7. Also plays a key role in degradation of mitochondrial RNA and processing of non-coding RNA imported from the cytosol into mitochondria. Participates as well in degradation of mitochondrion-associated cytosolic rRNAs.
Synonyms: RNASE6PL; FLJ10907; bA514O12.3
Tractability: Antibody: UniProt places it where antibodies can reach, with high confidence; its Gene Ontology location is reachable by antibodies, with high confidence; UniProt predicts a signal peptide or a membrane-spanning region. PROTAC: ubiquitination databases record sites on it.
Gene: Protein-coding gene on chromosome 6 (166,922,113 to 166,957,448, reverse strand). Ensembl gene ENSG00000026297.
Subcellular location: Secreted; Lysosome lumen; Endoplasmic reticulum lumen; Mitochondrion intermembrane space
Pathways (Reactome):
Immune System: Neutrophil degranulation
Gene Ontology:
Molecular function: ribonuclease T2 activity; RNA binding
Biological process: innate immune response; RNA catabolic process
Cellular component: endoplasmic reticulum lumen; extracellular exosome; extracellular region; lysosomal lumen; mitochondrial intermembrane space; azurophil granule lumen
Genetic constraint (gnomAD): Loss-of-function variants: 10 observed, 13.85 expected, observed/expected ratio (o/e) 0.72, 90% interval 0.44 to 1.22. The upper end of that interval is the gene's LOEUF score, 1.22, which puts it in group 5 of 6, group 1 being the genes least tolerant of losing a copy. Missense variants: 214 observed, 215.07 expected, observed/expected ratio (o/e) 1, 90% interval 0.89 to 1.11. Synonymous variants: 91 observed, 85.13 expected, observed/expected ratio (o/e) 1.07, 90% interval 0.9 to 1.27.
Homologues: Orthologues: chimpanzee RNASET2 (99% identical), macaque RNASET2 (96% identical), dog RNASET2 (71% identical), mouse Rnaset2a (69% identical), mouse Rnaset2b (69% identical), rat Rnaset2 (68% identical), guinea pig RNASET2 (62% identical), tropical clawed frog rnaset2 (45% identical), zebrafish rnaset2 (43% identical), Drosophila melanogaster RNaseX25 (29% identical), Caenorhabditis elegans rnst-2 (27% identical).
Diseases named in the same sentence as RNASET2 in open-access papers:
RNASET2 is named in the same sentence as 91 diseases in open-access papers, as found by Europe PMC text mining. Sharing a sentence is not in itself a finding about the gene and the disease. The quoted sentences say what the papers report.
ovarian carcinoma (17 papers, 2011 to 2025). A malignant neoplasm originating from the surface ovarian epithelium. "A direct FBOX6–RNASET2 interaction was demonstrated to be essential for FBOX6-mediated RNASET2 degradation, and FBOX deficiency was found to stabilize RNASET2 protein levels, leading to suppression of ovarian cancer cell proliferation, migration, and invasion." (PMID 37626657, 2023). "A TCGA survey for the RNASET2 mutation was recently carried out showing a 1 to 5% mutation rate for this gene in a wide range of human cancer types, with ovarian cancer showing as one of the highest rates." (PMID 36012339, 2022). "We next performed IHC analysis to evaluate the potential association between FBXO6 and RNASET2 in 88 human ovarian cancer specimens." (PMID 33767133, 2021). "In keeping with experimental data suggesting its role as a tumor suppressor, RNASET2 expression has been so far associated to less aggressive phenotypes in several cancer models, including ovarian cancer." (PMID 30813308, 2019). "Moreover, the downregulated expression of RNASET2 is generally associated with drug resistance in the treatment of ovarian cancer." (PMID 36728187, 2023). "Collectively, these data strongly suggested that RNASET2 expression in both ovarian cancer cell models is associated with a less aggressive tumor phenotype in terms of cell proliferation, with inhibition of ECM-dependent src kinase activation as a plausible underlying mechanism." (PMID 36012339, 2022). "Finally, an IHC survey on 88 human ovarian cancer specimens unveiled a negative correlation between FBXO6 and RNASET2 proteins expression, further pointing at a causal link between downregulation of RNASET2 protein in ovarian cancer and FBXO6 overexpression." (PMID 36012339, 2022). "Together, these results suggest that the downregulation of RNASET2 protein in ovarian cancer might be caused by FBXO6 overexpression." (PMID 33767133, 2021). "In addition, its overexpression inhibits the clonogenicity of ovarian cancer cells in vitro, indicating that RNASET2 may be implicated in the inhibition of tumor cell proliferation and survival." (PMID 34299186, 2021). "Finally, down-regulation of RNASET2 protein was associated with drug resistance in ovarian cancer." (PMID 32528897, 2020). "Conversely, in ovarian cancer, RNASET2 is a tumor suppressor by recruiting M1 macrophages to tumoral tissues." (PMID 39035989, 2024). "RNASET2 is a protein coding gene with a low expression level in ovarian cancers, but it is overexpressed in poorly differentiated neuroendocrine carcinomas." (PMID 36728187, 2023). "The migration and adhesion patterns were also found to be strongly affected by RNASET2 expression levels in stress-exposed OVCAR3 human ovarian cancer cells." (PMID 37626657, 2023). "Subsequent investigations confirmed the tumor-suppressive role of RNASET2 in ovarian cancer models by showing its ability to suppress the metastatic potential of a highly invasive and aggressive cancer cell line in vivo." (PMID 37626657, 2023). "Although several studies reported that RNASET2 is a tumor suppressor gene in ovarian cancer and melanoma, RNASET2 is overexpressed in poorly differentiated rather than in well‐differentiated neuroendocrine neoplasms of the lung." (PMID 36728187, 2023). "In several instances, RNASET2 levels were found to be decreased in advanced tumors, such as ovarian cancer, gastric cancer, and acute lymphocytic leukemia, as expected for a classical tumor suppressor gene and/or an alarmin-like molecule." (PMID 37626657, 2023). "The F-box FBOX6 protein (a subunit of the SCF complex) was found to act as a ubiquitin E3 ligase responsible for proteasome-mediated RNASET2 degradation in ovarian cancer models in vitro." (PMID 37626657, 2023). "This apparent trend was even more pronounced in fourteen human ovarian cancer-derived cell lines, 86% of which showed a clear downregulation in RNASET2 expression compared to normal primary ovarian cell lines." (PMID 36012339, 2022).
ovarian carcinoma (continued). "More specifically, among the RNASET2 alteration reported for ovarian cancer, 75% account as deep deletion and 25% as amplification." (PMID 36012339, 2022). "Much evidence, coming from different experimental models and tumor types, now also allow for proposing RNASET2 as a very promising candidate molecule for ovarian cancer characterization and potential therapy." (PMID 36012339, 2022). "Further in vivo data from human ovarian cancer tissues similarly showed a decreased RNASET2 expression in drug-resistant versus drug-sensitive tissues." (PMID 36012339, 2022). "Of note, they reported the interaction of the RNASET2 protein with FBXO6 in two human ovarian cancer cell lines (A2780 and OVCAR3)." (PMID 36012339, 2022). "FBXO6 directly interacts with the tumor suppressor gene RNASET2 to target it for ubiquitin-dependent degradation, thus functioning as an oncogene in ovarian cancer." (PMID 35368888, 2022). "Since most of the experimental data suggesting a role for RNASET2 in the control of ovarian cancer growth in vitro were derived from just two cell lines, further studies were carried out in other representative experimental models." (PMID 36012339, 2022). "The last two decades witnessed a more and more increased interest in the biology of RNASET2 in different cancer types, including ovarian cancer." (PMID 36012339, 2022). "The ubiquitination and degradation of FBXO6-mediated RNASET2 regulated the progress of ovarian cancer." (PMID 35938021, 2022). "Conversely, FBXO6 overexpression led to a marked decrease in RNASET2 protein expression in a dose-dependent manner, clearly suggesting that FBXO6 is involved in the degradation of RNASET2 protein in both ovarian cancer cell models." (PMID 36012339, 2022). "Based on these premises, the potential role of human RNASET2 as a tumor suppressor gene (TSG) involved in ovarian cancer control attracted the interest of several research groups long ago." (PMID 36012339, 2022). "According to this analysis, ovarian cancer ranks as third, in term of the alteration frequency of RNASET2." (PMID 36012339, 2022). "A2780 or OVCAR-3 cells treated with MLN4924 for 4 h also caused the accumulation of endogenous RNASET2 protein, suggesting RNASET2 is a substrate of CRLs in ovarian cancer cells." (PMID 33767133, 2021). "Our results revealed that silencing the expression of RNASET2 in FBXO6-depleted ovarian cancer cells promoted tumor growth in vivo." (PMID 33767133, 2021). "Our results not only reveal a regulatory mechanism of FBXO6 on RNASET2 protein but also uncover that the oncogenic effect of FBXO6 in ovarian cancer partly depends on the degradation of RNASET2." (PMID 33767133, 2021). "Previous reports have shown that RNASET2 is overexpressed in ovarian cancer lines in response to several stress conditions, including hypoxia." (PMID 34299186, 2021). "An inverse correlation between the protein levels of FBXO6 and RNASET2 was observed in clinic ovarian cancer samples." (PMID 33767133, 2021). "In genome-wide RNAi proliferation screening dataset, we set RNASET2 dependency score of ovarian cancer cell lines as a positive control due to RNASET2 was a known tumor suppressor gene in ovarian cancer." (PMID 32528897, 2020). "Of particular relevance, RNASET2 was shown by our group to signal to the innate immune system in in vivo xenograft-based models of human ovarian cancer by attracting host macrophages to the tumor mass and possibly contributing to their M1 polarization." (PMID 30813308, 2019). "Our group initially chose human ovarian carcinoma as an experimental model to test the role of RNASET2 as a tumor suppressor gene." (PMID 31749812, 2019). "Here, we aimed to investigate the effects of RNASET2 expression modulation on cell phenotype and behavior in epithelial ovarian cancer (EOC) cellular models." (PMID 30813308, 2019).
ovarian carcinoma (continued). "Despite the observed trend for a general increase in RNASET2 expression in ovarian cancer cells, this response involved different isoforms of the protein, depending on the nature of applied stress." (PMID 25797262, 2015). "Taken together, these results suggest a general role for the human RNASET2 as a stress-response gene in human ovarian cancer cells." (PMID 25797262, 2015). "Our previous results in ovarian cancer models strongly suggested a primarily non–cell autonomous role for RNASET2, whose in vivo tumor suppressive activity was shown to rely on the modulation of the host immune response." (PMID 25797262, 2015). "This is in agreement with our recent data on a mouse model of ovarian carcinoma, where catalytically-inactivated RNASET2 was still able to control ovarian carcinogenesis." (PMID 25797262, 2015). "In an ovarian cancer model, we recently found that such oncosuppressive role relies on RNASET2-mediated in vivo recruitment of cells from the monocyte/macrophage lineage in the tumor mass." (PMID 25797262, 2015). "This was basically the rationale that prompted us to further investigate the cell-autonomous expression profile induced by RNASET2 in ovarian cancer cells." (PMID 21646684, 2011). "As previously reported, using the Hey3Met2 human ovarian cancer cell line, we found the RNASET2 gene to possess a remarkable in vivo tumor suppressor activity, irrespective of the protein’s catalytic activity." (PMID 21646684, 2011). "In a xenograph model for ovarian cancer, we found RNASET2 to carry out a strong oncosuppressive activity by recruiting cells of the monocyte/macrophage lineage into the tumour mass." (PMID 21646684, 2011). "The putative role of RNASET2 in human ovarian cancer suppression was later supported by a report showing a marked downregulation of RNASET2 expression in both carboplatin- and cisplatin-resistant A2780 ovarian cancer cell lines compared to their parental counterparts." (PMID 37626657, 2023). "A wider range of cellular stresses was subsequently found to trigger a marked increase in RNASET2 expression and secretion in several ovarian cancer cell lines, and stress-induced RNASET2 overexpression was in turn associated with decreased clonogenic potential and decreased growth in soft agar." (PMID 37626657, 2023). "Some studies showed that RNASET2 plays a role as an antitumor gene in ovarian cancer and melanoma." (PMID 36728187, 2023). "Recent studies in ovarian cancer models suggest that RNASET2 contributes to maintaining the balance of M1/M2 macrophages in the tumor environment and may impact upon T cell adaptive immune memory response." (PMID 36466822, 2022). "Thus, the key role of macrophages in in vivo RNASET2-mediated tumor suppression was confirmed in an independent ovarian cancer experimental model." (PMID 36012339, 2022). "Moreover, RNASET2 protein has been reported to be targeted for FBXO6 unbiquitin-dependent protein degradation in ovarian cancer suggesting additional regulatory mechanism contribute to RNASET2 protein turnover." (PMID 36466822, 2022). "In the context of ovarian cancer and lymphoma, RNASET2 functions as an oncosuppresor." (PMID 36466822, 2022). "Therefore, the in vivo oncosuppressive role of RNASET2 was further investigated in a more conventional ovarian cancer cell model, represented by the OVCAR3 cell line." (PMID 36012339, 2022). "Based on these preliminary data, further investigations focused on the effects of RNASET2 overexpression or silencing in several models of human ovarian carcinoma were carried out to finally unveil a highly pleiotropic oncosuppressor role carried out by this gene." (PMID 36012339, 2022). "Thus, a key cancer-related feature, such as cell growth, was found to be modulated by RNASET2 in this ovarian cancer cell model." (PMID 36012339, 2022).
ovarian carcinoma (continued). "A detailed investigation on the mode of action of RNASET2 in ovarian cancer cells was later reported in the less aggressive, RNASET2-expressing OVCAR3 cell line and unveiled a highly pleiotropic role for this gene in modulating several in vitro cancer-related parameters." (PMID 36012339, 2022). "On the contrary, RNASET2 was downregulated in those ovarian cancer samples (53/88, 60.2%)." (PMID 33767133, 2021). "Given the critical roles of RNASET2 in inhibiting the development of ovarian cancer, specific RNASET2 agonists might produce some positive clinical effects." (PMID 33767133, 2021). "Depletion of FBXO6 promoted ovarian cancer cells proliferation, migration, and invasion, which could be partially reversed by RNASET2 silencing." (PMID 33767133, 2021). "Indeed, two independent in vivo xenograft-based murine models of human ovarian cancer have been previously used to demonstrate a marked RNASET2-mediated in vivo tumor suppression." (PMID 32197460, 2020). "In addition to its ribonuclease capacity, RNASET2 has been reported to exert anti-angiogenic and anti-tumorigenic effects in several tumor cell lines, such as colon cancer, breast cancer, and ovarian cancer." (PMID 32528897, 2020). "Up-regulation of RNASET2 protein significantly reduced the metastatic potential of ovarian cancer." (PMID 32528897, 2020). "RNASET2 was reported to be a tumor suppressor gene in ovarian cancer." (PMID 32528897, 2020). "Interestingly, we showed the RNASET2 gene to be frequently downregulated in both ovarian cancer-derived cell lines and tumor samples." (PMID 31749812, 2019). "Moreover, gene expression analysis in two human cancer types (ovarian cancer and chronic lymphocytic leukemia) unveiled a gradual decrease of RNASET2 gene expression with increasing stage or grade (which is an expected pattern for an oncosuppressor gene)." (PMID 31749812, 2019). "Moreover, changes in RNASET2 expression levels turned out to affect several cancer-related parameters in vitro in an ovarian cancer cell line model." (PMID 25797262, 2015). "As secretion of RNASET2 seemed to represent a critical step for its biological function, we further validated this hypothesis in our previously established ovarian cancer xenograft model." (PMID 25797262, 2015). "This role for the NK-κB pathway in macrophage polarization might therefore be relevant, considering that RNASET2 is apparently able to recruit specific subclass of stromal macrophages in the Hey3Met2 ovarian cancer model studied by our group." (PMID 21646684, 2011). "Furthermore a RNASET2-knock-down model recently established in our laboratory in the OVCAR3 ovarian cancer cell line will further contribute to investigate this issue." (PMID 21646684, 2011). "We next investigated whether FBXO6 regulates ovarian cancer progress through RNASET2 degradation." (PMID 33767133, 2021). "However, it is still unclear how RNASET2 protein is regulated in ovarian cancer." (PMID 33767133, 2021). "A first study used the RNASET2-null human Hey3Met2 cell line, derived from a highly metastatic subclone from the HEY4 ovarian cancer cell line." (PMID 36012339, 2022). "For instance, ectopic expression of human RNASET2 in the highly malignant RNASET2-nonexpressing HEY3MET2 ovarian cancer cell line was found to significantly suppress its tumorigenic potential in nude mice, independently from the protein’s catalytic activity." (PMID 37626657, 2023). "Here, we review and discuss the cell-autonomous and non-cell autonomous role of RNASET2 in the context of ovarian cancer, as a tumor suppressor gene." (PMID 36012339, 2022). "Within this frame, the role of RNASET2 as a non-cell autonomous tumor suppressor was further investigated by in in vivo by ovarian cancer cells tumor xenografts." (PMID 36012339, 2022).
ovarian carcinoma (continued). "However, the impaired migration and invasion abilities of FBXO6-depleted ovarian cancer cells were largely restored when RNASET2 was simultaneously silenced, suggesting a functional interplay between FBXO6 and RNASET2 proteins in ovarian cancer cells." (PMID 33767133, 2021). "We further found that there was a negative correlation between RNASET2 and FBXO6 protein in clinical ovarian cancer samples, suggesting that blocking the interaction between FBXO6 and RNASET2 might be a novel anti-ovarian cancer strategy." (PMID 33767133, 2021). "Importantly, decreased expression of RNASET2 is beneficial for ovarian cancer development and, independent of its enzymatic activity, is most likely related to activation of the innate immune response and modulation of extracellular matrix protein components." (PMID 33767133, 2021). "Moreover, a negative correlation between FBXO6 and RNASET2 proteins was observed in those ovarian cancer samples (χ2 = 13.41, P < 0.001)." (PMID 33767133, 2021). "Indeed, by comparing control vs. RNASET2-KD OVCAR3 cells, the expression pattern of several miRNAs turned out to be modulated, among which were miR-200c and miR-141, which were previously reported to be dysregulated in several human cancer types, including ovarian carcinoma." (PMID 36012339, 2022).